PDCL3 (phosducin like 3)
Diseases named in the same sentence as PDCL3 in open-access papers (continued):
Sharing a sentence is not in itself a finding about the gene and the disease.
tumor (5 papers, 2019 to 2025). "The relationship between PDCL3 expression and immune infiltration, tumor mutation burden (TMB), and microsatellite instability (MSI) was investigated." (PMID 40709189, 2025). "TF GATA1 could positively regulate target gene PDCL3, which was modified by DNA methylation, to cause tumor cell proliferation and angiogenesis through signaling transduction protein PDK2." (PMID 31126066, 2019). "Taken together, the immune infiltration analysis indicates that PDCL3 expression consistently showed a positive correlation with Th2 cell infiltration across all tumor types, while it was inversely correlated with pDC infiltration, except in LIHC." (PMID 40709189, 2025). "Survival analyses from the TCGA database revealed a worse outcome for tumor samples with upregulated PDCL3 expression." (PMID 40709189, 2025). "Subsequently, we assessed the relationship between PDCL3 and tumor stage, and the results indicated that PDCL3 expression was correlated with T stage in ACC, BRCA, LIHC, and LUAD, lymph node metastasis in ACC, HNSC, and LUAD, and distant metastasis in KIRP." (PMID 40709189, 2025). "The cBioPortal database was used to analyze genetic alterations of PDCL3 across different tumor types." (PMID 40709189, 2025). "This study primarily explored the relationship between PDCL3 and the tumor microenvironment, focusing on immune infiltration." (PMID 40709189, 2025). "To further explore the potential of PDCL3 in tumor immunotherapy, we investigated its relationship with TMB and MSI." (PMID 40709189, 2025). "The results showed that PDCL3 expression in tumor tissues was significantly higher than in normal tissues." (PMID 38494503, 2024). "TCGA and TIMER databases showed that high PDCL3 expression in LIHC decreased tumor immune activity by reducing macrophage infiltration." (PMID 38494503, 2024). "Immunohistochemistry (IHC) images from the HPA database depicted higher PDCL3 expression in tumor tissues." (PMID 38494503, 2024). "In conclusion, the functional enrichment results suggest that PDCL3 may play a role in tumor progression through both the cAMP and calcium signaling pathways." (PMID 40709189, 2025). "However, there is no pan-cancer analysis, and few studies have explored the effect of PDCL3 on tumor immune infiltration." (PMID 40709189, 2025). "Furthermore, differences in tumor-infiltrating immune cell abundance were determined between high and low PDCL3 expression groups." (PMID 38494503, 2024). "The results reflected that PDCL3 not only revealed satisfactory prognostic efficiency, similar to age, tumor grade, IDH status, 1p19q codeletion and MGMT promoter unmethylated status, but was also an independent predictor in the multivariate Cox regression analysis." (PMID 37006287, 2023). "Consequently, PDCL3-mediated reduction in VEGFR-2 degradation may significantly contribute to rapid tumor growth." (PMID 38494503, 2024). "Thus, PDCL3 is considered an essential gene in promoting tumor growth and proliferation." (PMID 38494503, 2024). "Angiogenesis is a critical process in tumor metastasis, driven by VEGFR-2, and PDCL3 can bind to VEGFR-2 to inhibit its degradation and ubiquitination, thereby regulating tumor progression." (PMID 40709189, 2025). "We found an inverse correlation between PDCL3 expression and CD8+ T cell infiltration in ACC, BRCA, and LUAD, suggesting the potential role of PDCL3 in modulating anti-tumor immunity." (PMID 40709189, 2025). "The representative IHC images of normal/tumor and low/high grade tissues from HPA revealed that the degree of staining intensity of CD96, DDB1, IP6K2, PDCL3, TRIM38, and KCNJ15 were in correspondence with our predictions of coefficient." (PMID 34268106, 2021). "PDCL3 staining in normal liver tissues was negative or moderate, while it was moderate or intense in tumor tissues." (PMID 38494503, 2024). "First, we did not design an ideal patient-derived tumor xenograft (PDX) model to verify the effects of PDCL3 in vivo." (PMID 37006287, 2023).
tumor (continued). "Additionally, PDCL3 enhances pathological angiogenesis by increasing tyrosine phosphorylation induced by vascular endothelial growth factor (VEGF), playing a central role in tumor growth." (PMID 38494503, 2024).
cancer (4 papers, 2020 to 2025). A tumor composed of atypical neoplastic, often pleomorphic cells that invade other tissues. "Our analysis revealed that PDCL3 alterations in cancer were primarily mutations and amplifications, with the most common alteration type being missense mutations." (PMID 40709189, 2025). "In summary, our study explored the potential of PDCL3 as a diagnostic and prognostic marker in tumors, highlighted its role in immune regulation, and provided new insights into cancer progression and immunotherapy research." (PMID 40709189, 2025). "This study aimed to comprehensively analyze the expression, diagnostic and prognostic value, immune regulation, gene mutation, and potential function of PDCL3 in pan-cancer, revealing its role in cancers at the single-cell transcriptome level." (PMID 40709189, 2025). "In our pan-cancer data analysis, we observed a close association between PDCL3 and LIHC." (PMID 38494503, 2024). "The association of PDCL3 with cancer progression remains unknown, and further study will be needed." (PMID 32039517, 2020). "In STAD, the expression of PDCL3 was most prominent in cancer cells, chief cells, endocrine cells, endothelial cells, fibroblasts, myeloid cells, and T cells." (PMID 40709189, 2025). "In LIHC, PDCL3 was predominantly expressed in cancer cells, dendritic cells, exhausted T (Tex) cells, hepatic progenitor cells, hepatic stellate cells, hepatocytes, and macrophages." (PMID 40709189, 2025). "By analyzing the expression of PDCL3 in LUAD cell clusters, it was found that PDCL3 expression was mainly in cancer cells, lung cells, M1 macrophages, M2 macrophages, mast cells, natural killer cells, plasma cells, and T cells." (PMID 40709189, 2025). "Single-cell dataset analysis confirmed that PDCL3 expression was primarily in cancer cells and macrophages." (PMID 40709189, 2025). "In our results, we confirmed that PDCL3 was overexpressed in nearly all types of malignant tumors in the TCGA dataset." (PMID 40709189, 2025). "Analysis of PDCL3 expression in BRCA cell clusters revealed that PDCL3 expression was primarily in cancer cells, macrophages, and pericytes." (PMID 40709189, 2025). "PDCL3 was demonstrated to be a potential marker for pan-cancer diagnosis and immunotherapy, and its high expression was closely related to the poor prognosis in cancer patients." (PMID 40709189, 2025). "Prognostic analysis using GEPIA indicated that high PDCL3 expression correlated with worse prognosis in various cancer types, including ACC, KICH, LGG, LUAD, LIHC, MESO, and UVM." (PMID 38494503, 2024). "This study aims to explore the prognostic value and potential mechanisms of PDCL3 in cancer, particularly in LIHC, through bioinformatics analysis." (PMID 38494503, 2024). "PDCL3 positively influenced the cell cycle, DNA damage and repair, inflammation, cell invasion and metastasis, and cancer stemness." (PMID 37006287, 2023). "DNA methylation and RNA methylation, including N1-methyladenosine (m1A), cytosine-5-methylation (m5C) and N6-methyladenosine (m6A), are the most common DNA and RNA modifications, so we explored their correlations with PDCL3 expression levels across cancers." (PMID 37006287, 2023). "We first analyzed the relationship between PDCL3 expression and cancer stemness across cancers by calculating six different stemness indexes." (PMID 37006287, 2023). "PDCL3 expression was positively correlated with most of the 150 common immunomodulators across cancers." (PMID 37006287, 2023). "PDCL3 may contribute to cancer progression and is a potential candidate biomarker for pan-cancer diagnosis and prognosis." (PMID 40709189, 2025). "In the analysis of single-cell datasets, PDCL3 expression was detected at high levels in LUAD, LIHC, BRCA, and STAD cancer cells, with PDCL3 upregulated in IAC, suggesting that PDCL3 may promote the invasive growth of LUAD." (PMID 40709189, 2025). "The pan-cancer analysis results indicated that PDCL3 was upregulated in most cancers." (PMID 40709189, 2025).
cancer (continued). "In LUAD, the cancer-promoting mechanism of PDCL3 may involve the induction of angiogenesis through the regulation of T cell secretion functions." (PMID 40709189, 2025). "This study comprehensively investigated PDCL3 in pan-cancer, including an in-depth analysis of its expression differences, diagnostic and prognostic value, immune infiltration, and potential implications for immunotherapy, aiming to clarify the clinical effect of PDCL3 on cancer." (PMID 40709189, 2025). "In this study, we employed the Cancer Genome Atlas (TCGA), UALCAN, and other databases to investigate PDCL3 expression in pan-cancer and conducted an in-depth exploration of its expression, clinical relevance, prognostic impact, and functional implications in LIHC." (PMID 38494503, 2024). "Pan-cancer gene expression analysis of PDCL3 was conducted using various databases." (PMID 38494503, 2024). "In summary, our findings indicate that high PDCL3 expression predicts poorer overall survival (OS) and may serve as a potential prognostic marker for cancer." (PMID 38494503, 2024). "We first analyzed the expression profiles of PDCL3 in various human cancer tissues and cell lines." (PMID 37006287, 2023). "PDCL3 was positively correlated with the infiltration of multiple immune cells across cancers." (PMID 37006287, 2023). "In addition, cell function experiments confirmed that PDCL3 could enhance the proliferation, migration, and invasion of cancer cells." (PMID 40709189, 2025). "However, the precise regulatory mechanisms of PDCL3 in cancer warrant further investigation." (PMID 38494503, 2024). "Therefore, it is speculated that PDCL3 plays a key role in both cancer progression and treatment." (PMID 40709189, 2025). "However, the precise role of PDCL3 in cancer remains unclear." (PMID 38494503, 2024). "Pan-cancer analysis from GEPIA and TCGA databases demonstrates that elevated PDCL3 expression correlates with poorer outcomes in ACC, KICH, LGG, LUAD, LIHC, MESO, and UVM." (PMID 38494503, 2024). "RNA-seq data and corresponding clinical information for pan-cancer and LIHC were extracted from the TCGA database to analyze PDCL3 expression and survival prognosis." (PMID 38494503, 2024). "Additionally, the direct mechanism of PDCL3 in cancer has not yet been confirmed, and further experimental studies are needed to better understand its precise role." (PMID 40709189, 2025).
PDCL3 also shares sentences with these, for which no sentence is quoted: breast invasive carcinoma (2 papers); lung adenocarcinoma (2); lung squamous cell carcinoma (2); cholangiocarcinoma (1); esophageal carcinoma (1); head and neck squamous cell carcinoma (1); kidney chromophobe (1); ovarian carcinoma (1); pancreatic adenocarcinoma (1); prostate adenocarcinoma (1); prostate carcinoma (1); rectum adenocarcinoma (1).